IL6 (interleukin 6)
Diseases named in the same sentence as IL6 in open-access papers (continued):
Sharing a sentence is not in itself a finding about the gene and the disease.
colitis (continued). "Inflammatory cytokines such as IL-6, TNF-α, and interferon-γ mediate the pathogenesis of murine colitis." (PMID 24194783, 2013). "At 15 DPI in mice with colitis, the production of IL-12p70 and MCP-1 increased and production of regulatory cytokines TGF-β, IL-10 and IL-6 decreased." (PMID 24167594, 2013). "This increase in severity of colitis observed in 5-HTP treated groups was also resulted in increased levels of colonic IL-1β and IL-6." (PMID 24015275, 2013). "The levels of the inflammation-related cytokines IL-6 and TNF-α were used to determine the preventative effects on dextran sulfate sodium (DSS)-induced colitis in mice." (PMID 24223664, 2013). "Pro-inflammatory cytokines such as TNF-α, IL-1β, and IL-6 were detectable in both SIGNR3−/− and wild-type mice upon induction of DSS colitis." (PMID 23882266, 2013). "Proinflammatory cytokines (e.g., TNF-α, IL-1β, and IL-6) liberated from macrophages, neutrophils, and endothelial cells were shown to be overproduced in TNBS-induced colitis and in human IBD." (PMID 22888336, 2012). "In both experimental colitis models, TNF-α and IL-6 levels were elevated but treatment with iMSCs was accompanied by a strong reduction in the amount of TNF-α and IL-6 in the colon." (PMID 23049573, 2012). "We generated a mouse model of experimental colitis induced by dextran sulfate sodium (DSS) and showed that IL-6 triggered S100A9 production in CECs, which was mediated through STAT3 activation." (PMID 22962574, 2012). "Its administration attenuated the development of signs and symptoms of colitis, reduced colonic expression of TNF-α, Interleukin (IL)-6, and IFN-γ, and reserved colonic down-regulation of PPAR-γ, PXR, and FXR caused by a TNBS model of induced colitis." (PMID 23251142, 2012). "Colons and mesenteric lymph nodes were harvested 7 days after the induction of colitis, and the expression of IFN-γ, IL-6, IL-17, IL-4, and IL-10 mRNA was quantified by real-time PCR." (PMID 22479648, 2012). "In a model of angiogenesis, higher levels of IL-6 are secreted by TSP-1−/− aortic explants, and similar results are found in a mouse model of colitis." (PMID 21765615, 2011). "Along with the higher number of immune cells in the colitis + HFD group, we found overexpression of TNFα, IL-6 and MCP1/CCL2 compared to the other three groups." (PMID 22073943, 2011). "Rb1 and compound K appear to block IRAK-1 and NFκB activation and thereby reduce pro-inflammatory cytokines, IL-1β, TNF-α and IL-6 and cytokine effectors iNOS and Cox-2 in 2,4,6-trinitrobenzene sulfonic acid (TNBS)-treated mice, another model of colitis." (PMID 22070864, 2011). "Meanwhile, the levels of colonic TNF-α, IL-6, and IFN-γ in colitis mice were significantly higher than that in control mice, and treatment with AMD3100 markedly reduced the cytokines levels in colitis mice." (PMID 22073304, 2011). "There is a statistically significantly lower production of IL-6 and IFN-γ in DSS/6-TG 40 treated mice, as compared to DSS/PBS- or DSS/AZA 60 treated mice in the acute colitis model." (PMID 21545711, 2011). "We examined levels of IL-6, IL-10, IL-17A, and IL-23 in the colons following 7 days of cis-UCA treatment, and also following the induction of colitis." (PMID 21060867, 2010). "Marked induction of IL1β, IL6, TGFβ and IL23A, genes involved in the differentiation of Th17 cells, was observed in colonic inflammation." (PMID 21144017, 2010). "Examining the expression of cytokines, we found significantly elevatedmRNA levels of proinflammatory cytokines IL-1β, IL-6, GM-CSF, and TNFα in micewith TNBS-induced colitis." (PMID 18288268, 2007). "Relative amounts ofIL-1β, IL-6, GM-CSF, and TNFα mRNAs (for full gene names) weresignificantly higher in animals with TNBS-induced colitis (group D) than in thecontrol sham-treated animals." (PMID 18288268, 2007).
colitis (continued). "In a DSS-induced murine model of colitis, matrine treatment mitigated disease symptoms, reduced key inflammatory markers (IL-1β, TNF-α, IL-6) and oxidative stress indicators (including ROS), and restored bile acid homeostasis by upregulating transporters (MRP3 and MRP4) and bile acid receptor FXR." (PMID 41882686, 2026). "Additionally, PPE can alleviate inflammatory symptoms of colitis and reduced serum levels of the inflammatory markers (TNF-α, IL-6, and CRP) owing to its anti-inflammatory properties." (PMID 40359212, 2025). "In conclusion, DBK successfully reduced inflammation in DSS-induced UC mice by modulating the IL-6/IL-6R and IL-17A/IL-17RA pathways, as evidenced by alleviated colitis symptoms, decreased pro-inflammatory cytokines (TNF-α, IL-6, IL-1β), and histological improvements." (PMID 40005956, 2025). "DNA hydroxy methylase 10–11 translocation protein 2 (TET2), a key dioxygenase responsible for DNA hydroxy methylation, has been demonstrated to regulate interleukin-6 (IL-6) levels and attenuate dextran sulfate sodium (DSS) - induced colonic inflammation in UC colon." (PMID 40650121, 2025). "For example, it has been demonstrated to possess a spectrum of anti-colitis effects, such as upregulating beneficial metabolites, downregulating pro-inflammatory cytokines (TNF-α and IL-6), restoring the intestinal mucosal barrier, and enhancing the host’s resistance to DSS-induced UC." (PMID 40002063, 2025). "CW supplementation inhibits the high levels of inflammation induced by DSS, suppressing excessive inflammatory mediators (serum TNF‐α, IL‐1β, and IL‐6), downregulating the overexpressed mRNA levels of TNF‐α, IL‐1β, IL‐6, TLR4, and iNOS, while upregulating IL‐10, thereby alleviating colitis." (PMID 39830908, 2025). "Therapy with nicotine reduced TNF production in the colon and improved colitis, but subdiaphragmatic vagotomy of the ventral and dorsal vagus nerves raised the colitis disease activity score and markedly elevated TNF, IL-6, and IL-1b production in colon tissue." (PMID 39828740, 2025). "Also, ELISA results showed that markers of M1 macrophages (iNOS, IL-6, TNF-α) in colon tissue increased significantly during the colitis stage." (PMID 40370742, 2025). "In vivo experiments, using mice with induced colitis, showed only a mild amelioration in clinical signs of colitis, but a significant reduction in total colon weight and colonic mRNA expression of TNF-α and IL-6, compared to the control group." (PMID 40871103, 2025). "It has been reported that, in DSS-induced colitis models, ginger-derived nanoparticles were found to be predominantly absorbed by intestinal epithelial and immune cells, decreasing pro-inflammatory cytokines (TNF-α, IL-6), and improving barrier function." (PMID 41383462, 2025). "Moreover, dietary resveratrol attenuated the inflammatory status and down-regulated the expression of proinflammatory cytokines such as IL-2, IFN-γ, IL-1β, IL-6, and TNF-α in colitis mouse model." (PMID 40078988, 2025). "Additionally, Rhy lowered serum levels of inflammatory cytokines IL-6, TNF-α, CXCL1, and IL-1β in colitis mice." (PMID 41031160, 2025). "Moreover, given the intense inflammatory response characterizing colitis, we examined the gene expressions related to inflammation in colon tissue, including tumor necrosis factor α (TNF-α), interleukin-6 (IL-6), and interleukin-1β (IL-1β)." (PMID 40000617, 2025). "Moreover, studies using anti-TNF-α and anti-IL-6 monoclonal antibodies have demonstrated that reducing TNF-α and IL-6 levels significantly alleviates colonic damage in colitis." (PMID 41227760, 2025). "In a DSS-induced experimental colitis model in rats, PNS demonstrated the ability to suppress the PI3K/Akt signaling pathway, reduce oxidative stress, and lower pro-inflammatory cytokines such as IL-6, IL-1β, and TNF-α." (PMID 40417220, 2025).
colitis (continued). "Furthermore, it decreased pro-inflammatory cytokines (IL-6, IL-23, and TNF-α) and STAT3 pathway phosphorylation, leading to IL-17 silencing and suppression of colitis." (PMID 41465447, 2025). "It was shown that increased O-linked N-acetylglucosamine modification (O-GlcNAcylation) of STAT3 upregulated the expression of proinflammatory cytokines such as IL-6, IL-1β, and TNF-α, while downregulating the level of the anti-inflammatory cytokine IL-10 and aggravating colitis in mice." (PMID 40078988, 2025). "Interestingly, EGFR-STAT3 activation in myeloid cells protects mice from colitis induction by dextran sodium sulfate treatment (DDS), via regulation of IL-6 production, which prevents intestinal damage leading to IEC proliferation." (PMID 39966897, 2025). "IL-1β and IL-6 serum levels were significantly higher in the model and CDP groups, while CEA and AFP levels exhibited similar trends, indicating that CDPs facilitate the development of internal tumors in colitis mice models." (PMID 40911847, 2025). "Furthermore, research has indicated that PG 97-269 may reduce the production of cytokines (IL-1β and IL-6) by immune cells, such as monocytes, mast cells, and macrophages, whereas it also inhibits their chemotactic activity, thus holding therapeutic potential in the treatment of colitis." (PMID 39942672, 2025). "Additionally, as the results confirm the presence of IL-6 and TNF-α in the serum of the DSS-induced colitis mouse model, KMLE reduced the cytokines in the serum of the DSS-induced colitis mouse model." (PMID 40227441, 2025). "Our study contributes valuable insights into the potential therapeutic applications of herbal-based therapies for chronic inflammatory conditions, emphasizing the role of PPPG in modulating the IL-6/STAT3 pathway and demonstrating its efficacy in a preclinical model of colitis." (PMID 40733052, 2025). "Furthermore, SPDD weakened the interaction between MAPK4 and AKT, resulting in a decrease in the phosphorylation level of AKT, thereby reducing the expression of IL-6, IL-1β, iNOS, and COX-2, and alleviating colitis (p < 0.05)." (PMID 40238233, 2025). "Conversely, L. plantarum T10 failed to reduce IL-6 levels in colitis models, while other L. plantarum strains showed potent anti-inflammatory effects." (PMID 41301527, 2025). "Several experimental studies have investigated the therapeutic potential of PTX in models of colitis; however, the present study is the first to elucidate its modulatory effects on the SPHK1/S1P, IL‐6/STAT3, AMPK/mTOR/NLRP3, and ZO‐1 signaling pathways in experimental colitis." (PMID 40387460, 2025). "These infiltrates are typically accompanied by increased levels of proinflammatory cytokines, including IL-6/17, interferon-gamma (IFN-γ), and tumor necrosis factor alpha (TNF-α), which are thought to mediate mucosal injury and contribute to the severity of colitis." (PMID 40726872, 2025). "In this study, the levels of IL-1β, IL-6, and TNF-α in enteritis model mice were significantly higher than those in the control group, indicating that systemic inflammation was triggered when DSS-induced colitis." (PMID 40238292, 2025). "The DSS group showed a significant increase in the gene expression levels of TNF-α, IL-1β, and IL-6 in the colon (p < 0.001), which was consistent with the serum findings, indicating a strong correlation between DSS-induced colitis and heightened cytokine expression in the colon." (PMID 40238198, 2025). "Moreover, levels of pro-inflammatory cytokines including IL-6, IL-1β, and TNF-α were notably reduced, whereas anti-inflammatory cytokine IL-10 was notably increased after YTA treatment in colitis mice." (PMID 41476793, 2025). "We hypothesized that the selective inhibition of STAT3 by HCB-5300 and HCB-5400 would mitigate colonic injury, suppress pro-inflammatory cytokine expression (e.g., IL-6), and improve histopathological outcomes in DSS-induced colitis." (PMID 41465408, 2025).
colitis (continued). "Moreover, flavonoid‐rich extracts from okra flowers (AFE) significantly inhibit colitis and the formation of AOM/DSS‐induced CAC by influencing the Nrf2/IL‐6 signaling pathway." (PMID 40548181, 2025). "In a DSS-induced murine colitis model, liraglutide treatment significantly reduced histological inflammation scores (from 7.4 ± 0.3 to 2.2 ± 0.5, p < 0.001), and suppressed TNF-α and IL-6 expression by over 60%." (PMID 40917833, 2025). "It has been reported that Houttuynia Chordata, a traditional medicinal plant, decreased inflammatory cytokines, such as IL-6 and TNF-α, and increased the level of anti-inflammatory IL-10 and various tight junction proteins in a dextran sulfate sodium-induced colitis model." (PMID 40149930, 2025). "Moreover, ELISA analyses demonstrated that quercetin alleviated colonic inflammation by significantly decreased the levels of IL-1β, IL-6, and TNF-α by 23.2 %, 19.9 %, and 20.7 %, respectively, in colitis mice." (PMID 40909112, 2025). "Furthermore, compared with the control group, RT-PCR revealed that there was an obvious increase in the expression of the typical inflammation-related cytokines, mainly including TNF-α, IL-6, IL-1β, and iNOS in the DSS-induced colitis model." (PMID 40255504, 2025). "In mice with DSS-induced colitis, levels of the pro-inflammatory cytokines TNF-α, IL-1β, and IL-6 were significantly elevated, whilst the anti-inflammatory cytokine IL-10 was markedly decreased, indicating an intense inflammatory response and immune dysregulation." (PMID 40777179, 2025). "At the same time, the results of SAKAI showed that AST could inhibit the expression of inflammatory factors (IL-1β, IL-6, TNF-α, and COX-2) in mice and ultimately alleviate the development of colitis." (PMID 40867814, 2025). "In a DSS-induced colitis mouse study, puerarin markedly reduced colon inflammation by inhibiting the NF-κB pathway—treated mice had significantly lower myeloperoxidase activity and reduced levels of TNF-α, IL-1β, and IL-6 in colonic tissue." (PMID 41008518, 2025). "Similarly, QA has been shown to lower IL-1β, iNOS, IL-6, and TNF-α expression in a mouse colitis model." (PMID 40538727, 2025). "Interestingly, PPT with an anti-inflammatory effect (e.g., suppression of IL-6, IL-1β, and TNF-α) ameliorated colitis, resulting in the recovery of body weight and colon length." (PMID 40141242, 2025). "Moreover, these molecules have been demonstrated to inhibit the infiltration of TCD3+ cells and CD68+ macrophages in the intestinal mucosa, thereby alleviating colitis by reducing the production of pro-inflammatory cytokines TNF-α and IL6 by macrophages." (PMID 40130239, 2025). "ELISAs revealed significantly lower IL-17 and IL-6 levels in Gpr15−/− mice with TNBS-induced colitis with or without smoke exposure." (PMID 40957881, 2025). "When treated with a diet supplemented with L. plantarum 17-1, the levels of IL-6 and IL-17 were reduced in DSS-induced-colitis mice, which may help restore the disrupted balance in IBD patients, potentially alleviating symptoms and promoting recovery." (PMID 40284212, 2025). "In our work, the levels of TNF-α and IL-6 did not statistically significantly increase in Mcpt-4fl/fl colitis mice compared with that in control Mcpt-4fl/fl mice, but there was a minor increase." (PMID 40697820, 2025). "The extract effectively improved the reduction in body weight and the clinical manifestations of colitis, significantly ameliorated the clinical signs observed in UC, and decreased cytokine levels from the Th1 (IFN-γ, IL-12, and TNF-α) and Th17 (IL-6 and IL-17) immune response pattern." (PMID 39195452, 2024). "Thus, the levels of NO, TNF-α, IL-6, and PGE2 in the colon tissue of LPS-induced Caco-2/RAW264.7 cells and DSS-induced colitis mice were decreased." (PMID 39202931, 2024). "Similarly, P. gingivalis has been demonstrated to upregulate the expression of IL-6, TNF-α, and IL1-β and exacerbate colitis in DSS-induced mice." (PMID 38540299, 2024).
colitis (continued). "Besides elevating the LC3-II/LC3-I ratio, ATG5 and Beclin-1 levels and decreasing P62 level, the ANI/NEO combination decreased the expression of several inflammatory cytokines (INF-γ, TNF-α, IL-6, and IL-22) in colon tissue from mice with DSS-induced colitis." (PMID 38354108, 2024). "In another study that utilized a DSS-induced mouse model of colitis, we found that APS could regulate the expression of inflammatory cytokines, including IL-2, IL-6, IL-12p70, IL-23 and TNF-α, in the colonic tissues of mice with colitis." (PMID 38202824, 2024). "In addition, the mRNA levels of proinflammatory cytokines including Ccl5, IL-17, IL-6, TNF-α, IFN-γ, CXCL10, and Ccl8 were all found to be increased in colitis tissues of S100A4Smad4-/- mice compared with those in Smad4fl/fl mice." (PMID 39664586, 2024). "In the current study, the serum levels of IL-6 and TNF-α were prominently increased in DSS-induced colitis mice (p < 0.0001), which were significantly decreased after RL5 supplementation (p < 0.01), but RP6 did not significantly inhibit the alterations of TNF-α." (PMID 39594091, 2024). "Furthermore, in colitis mice treated with hUC-MSCs, there was a notable decrease in serum levels of IFN-γ, IL-1β, TNF-α and IL-6, as well as reduced the mRNA expression levels of Ifng, Il1b, Tnfa and Il6 in the colons." (PMID 38956621, 2024). "In vitro and in vivo studies also demonstrated that palmitic acid combined with oleic acid reduced inflammatory markers such as COX-2, TNFα, IL-6, and IL-12 in LPS-stimulated macrophages, and reduced inflammatory parameters in models of dextran sulfate sodium (DSS)-induced colitis in mice." (PMID 39339251, 2024). "Studies have reported that proinflammatory factors such as CD86 and IL-6 were elevated in IBD patients, and neutralization of IL-6 could relieve DSS-induced colitis." (PMID 38877444, 2024). "The concentrations of pro-inflammatory (IL6 and TGFβ) and anti-inflammatory (IL10) cytokines were determined to evaluate the immunoregulatory effects of recombinant L. strains in the context of DSS-induced colitis in mice." (PMID 38680913, 2024). "Increased expressions of Iba1, a marker of activated microglia, IL-6, TNF-α, and the cyclin-dependent kinase inhibitor p21 (p21) in the hippocampus were detected in the acute phase of DSS-induced colitis, while the overexpression of p21 persisted in the chronic phase." (PMID 38247868, 2024). "However, lactic acid bacteria enriched in the colitis group showed a strong inverse correlation with colonic TNF-α, IL-1β,and IL-6 levels (p < 0.05)." (PMID 38528541, 2024). "Similarly, previous research has also found that PA can effectively inhibit the elevation of IL-1β, IL-6, and TNF-α levels in colitis." (PMID 39064674, 2024). "In IBD patients, the levels of IL-6 and TNF-α production are significantly greater in the serum and tissues, and enhanced local or systemic inflammation disrupts TJs and leads to worsened colitis." (PMID 38790680, 2024). "In murine DSS-induced colitis, inosine attenuates the hallmarks of colitis and colonic levels of malondialdehyde (MDA), myeloperoxidase activity (MPO), major intrinsic proteins (MIP)-1α and -2 and proinflammatory cytokines IL-1, IL-6, IL-12 and TNF-α." (PMID 38474346, 2024). "Lactiplantibacillus plantarum HF05 could reduce the release of TNF-α and IL-6 from LPS-treated macrophages and the levels of TNF-α and IL-6 in DSS-induced colitis mice, thereby playing an anti-inflammatory role." (PMID 39594091, 2024). "Many studies have shown that cytokines IL-6, IL-1β, and TNF-α play an important role in colitis." (PMID 38398846, 2024). "Additionally, at doses of 20 and 40 mg/kg, ferulic acid ameliorated TNBS-induced colitis by inhibiting the production of proinflammatory cytokines (TNF-α, IL-1β, IL-6, AND IL-10) and downregulating COX-2 synthesis." (PMID 38732594, 2024).